ASTN1 (astrotactin 1)
Description:
Neuronal adhesion molecule that is required for normal migration of young postmitotic neuroblasts along glial fibers, especially in the cerebellum. Required for normal rate of migration of granule cells during brain development and for normal cerebellum development.
Synonyms: ASTN
Tractability: Antibody: UniProt places it where antibodies can reach, with medium confidence; UniProt predicts a signal peptide or a membrane-spanning region; its Gene Ontology location is reachable by antibodies, with medium confidence. PROTAC: its protein half-life has been measured.
Gene: Protein-coding gene on chromosome 1 (176,857,302 to 177,164,973, reverse strand). Ensembl gene ENSG00000152092.
Subcellular location: Cell membrane; Perikaryon; Endosome; Cytoplasmic vesicle, clathrin-coated vesicle
Subcellular location (Human Protein Atlas): Golgi apparatus; Vesicles
Gene Ontology:
Biological process: neuron cell-cell adhesion; neuron migration
Cellular component: endosome; membrane; clathrin-coated vesicle; external side of plasma membrane; perikaryon; plasma membrane
Genetic constraint (gnomAD): Loss-of-function variants: 41 observed, 135.8 expected, observed/expected ratio (o/e) 0.3, 90% interval 0.23 to 0.39. The upper end of that interval is the gene's LOEUF score, 0.39, which puts it in group 1 of 6, group 1 being the genes least tolerant of losing a copy. Missense variants: 1,429 observed, 1,681.6 expected, observed/expected ratio (o/e) 0.85, 90% interval 0.81 to 0.89. Synonymous variants: 619 observed, 656.91 expected, observed/expected ratio (o/e) 0.94, 90% interval 0.88 to 1.01.
Homologues: Orthologues: chimpanzee ASTN1 (99% identical), macaque ASTN1 (99% identical), mouse Astn1 (98% identical), rat Astn1 (98% identical), pig ASTN1 (98% identical), dog ASTN1 (96% identical), rabbit ASTN1 (92% identical), guinea pig ASTN1 (92% identical), tropical clawed frog astn1 (82% identical), zebrafish astn1 (79% identical). Paralogues in human: ASTN2 (50% identical).
Diseases named in the same sentence as ASTN1 in open-access papers:
ASTN1 is named in the same sentence as 18 diseases in open-access papers, as found by Europe PMC text mining. Sharing a sentence is not in itself a finding about the gene and the disease. The quoted sentences say what the papers report.
cervical cancer (3 papers, 2018 to 2025). A primary or metastatic malignant neoplasm involving the cervix. "In cervical cancer a DNA hypermethylation marker panel consisting of the six marker regions ASTN1, DLX1, ITGA4, RXFP3, SOX17, and ZNF671 may be a useful tool for triaging HPV-positive women." (PMID 30509219, 2018). "The aim was to investigate the diagnostic value provided by methylation biomarkers of six tumor suppressor genes (ASTN1, DLX1, ITGA4, RXFP3, SOX17 and ZNF671) for cervical precancerous lesions and cervical cancer." (PMID 36803573, 2023).
autism (1 paper, 2020). Persistent deficits in social interaction and communication and interaction as well as a markedly restricted repertoire of activity and interest as well as repetitive patterns of behavior. "Here we report a homozygous truncating variant [ASTN1:NM_001286164.2:c.3159_3160del;p.(Gln1053Hisfs∗13)] in a patient with autism, ADHD and seizures." (PMID 33456446, 2020).
cervical intraepithelial neoplasia (1 paper, 2025). "A panel of six methylation markers (ASTN1, DLX1, ITGA4, RXFP3, SOX17, ZNF671; GynTect® assay) has shown promise in diagnosing cervical intraepithelial neoplasia (CIN)." (PMID 40022051, 2025).
dementia (1 paper, 2011). Loss of intellectual abilities interfering with an individual's social and occupational functions. "Indeed, ASTN1 is known to regulate neuronal migration in cortical regions of developing brain, SNCA is associated with neurodegeneration and dementias, including links to FTLD-TDP in PGRN+ patients and REEP1 has been implicated in corticospinal neurodegenerative disorders." (PMID 22032330, 2011).
developmental delay (1 paper, 2020). "ASTN1 was reported as a candidate gene for brain malformation, and spastic tetraplegia, epilepsy and developmental delay." (PMID 33456446, 2020).
diabetes (1 paper, 2025). "Together, our findings suggest that circ-Astn1 is a promising diabetes diagnostic biomarker." (PMID 40014196, 2025). "Furthermore, our findings may facilitate expanded drug applications targeting circ-Astn1 and highlight a potential role for circ-Astn1 in diabetes treatment." (PMID 40014196, 2025).
dysplasia (1 paper, 2025). A usually neoplastic transformation of the cell, associated with altered architectural tissue patterns. "Five of the six markers (ASTN1, ITGA4, RXFP3, SOX17, and ZNF671) showed good positivity in vulvar dysplasia but with unexpected high positivity in VLSIL (VIN I) FFPE samples compared to higher dysplasia grades." (PMID 40022051, 2025).
glaucoma (1 paper, 2013). Increased pressure in the eyeball due to obstruction of the outflow of aqueous humor. "For example, Aqp4, astrotactin 1 (Astn1), contactin 1 (Cntn1), and gap junction protein alpha 1 (Gja1) were down-regulated after optic nerve crush, but were up-regulated in glaucoma." (PMID 23826199, 2013).
small cell lung carcinoma (1 paper, 2018). Small cell lung cancer (SCLC) is a highly aggressive malignant neoplasm, accounting for 10-15% of lung cancer cases, characterized byrapid growth, and early metastasis. "HOTAIR is relevant to small cell lung cancer invasiveness by suppressing cell adhesion–related genes such as astrotactin 1 (ASTN1) and protocadherin alpha 1 (PCDHA1)." (PMID 29618386, 2018).
neurodevelopmental disorder (2 papers, 2016 to 2026). A behavioral and cognitive disorder with onset during the developmental period that involves impaired or aberrant development of intellectual, motor, or social functions. "Genetic variation at the human BRINP2/ASTN1 and BRINP1/ASTN2 loci has been implicated in neurodevelopmental disorders." (PMID 27826231, 2016). "Two copy number variations (CNV)—one deletion and one duplication—are reported in patients with neurodevelopmental disorders (NDDs) that span the ASTN1/BRINP2 loci, suggesting that one or both of these genes is responsible for the neuropathology." (PMID 27826231, 2016).
tumor (1 paper, 2012). "In addition, CFTR was a chloride channel and the cause of cystic fibrosis; DHX57 was a putative ATP-dependent RNA helicase truncated in this TCC tumor; and ASTN1 was a neuronal adhesion molecule shown to be mutant in previous tumor studies." (PMID 23587365, 2012).
ASTN1 also shares sentences with these, for which no sentence is quoted: Alzheimer disease (1 paper); cancer (1); epilepsy (1); gastric cancer (1); Hyperglycemia (1); schizophrenia (1); Spastic tetraplegia (1).